LINC00458 (long independently transcribed non-coding RNA 458)
Synonyms: ES3; HBL1; LncRNA-ES3
Gene: Long non-coding RNA gene on chromosome 13 (53,950,255 to 54,270,397, reverse strand). Ensembl gene ENSG00000234787.
Diseases named in the same sentence as LINC00458 in open-access papers:
LINC00458 is named in the same sentence as 4 diseases in open-access papers, as found by Europe PMC text mining. Sharing a sentence is not in itself a finding about the gene and the disease.
LINC00458 shares sentences with these, for which no sentence is quoted: lymphoma (2 papers); cardiac diseases (1); CNS lymphoma (1); tumor (1).